LMAN1L (lectin, mannose binding 1 like)
Synonyms: ERGL; ERGIC-53L
Tractability: Antibody: UniProt predicts a signal peptide or a membrane-spanning region. PROTAC: its protein half-life has been measured.
Gene: Protein-coding gene on chromosome 15 (74,812,716 to 74,825,757, forward strand). Ensembl gene ENSG00000140506.
Subcellular location: Endoplasmic reticulum-Golgi intermediate compartment membrane
Pathways (Reactome):
Vesicle-mediated transport: COPII-mediated vesicle transport; Cargo concentration in the ER
Gene Ontology:
Molecular function: D-mannose binding
Biological process: endoplasmic reticulum to Golgi vesicle-mediated transport
Cellular component: extracellular matrix; COPII-coated ER to Golgi transport vesicle; endoplasmic reticulum membrane; endoplasmic reticulum-Golgi intermediate compartment; Golgi membrane; endomembrane system; endoplasmic reticulum-Golgi intermediate compartment membrane; membrane
Genetic constraint (gnomAD): Loss-of-function variants: 56 observed, 54.75 expected, observed/expected ratio (o/e) 1.02, 90% interval 0.82 to 1.28. The upper end of that interval is the gene's LOEUF score, 1.28, which puts it in group 5 of 6, group 1 being the genes least tolerant of losing a copy. Missense variants: 605 observed, 650.14 expected, observed/expected ratio (o/e) 0.93, 90% interval 0.87 to 1. Synonymous variants: 274 observed, 259.5 expected, observed/expected ratio (o/e) 1.06, 90% interval 0.96 to 1.17.
Homologues: Orthologues: chimpanzee LMAN1L (97% identical), macaque LMAN1L (90% identical), pig LMAN1L (74% identical), dog LMAN1L (68% identical), rabbit LMAN1L (67% identical), mouse Lman1l (66% identical), guinea pig LMAN1L (66% identical), rat Lman1l (64% identical), tropical clawed frog cplx3 (29% identical), Drosophila melanogaster ergic53 (28% identical), Caenorhabditis elegans ile-1 (26% identical), Caenorhabditis elegans ile-2 (16% identical), and 1 more. Paralogues in human: LMAN1 (33% identical), LMAN2 (19% identical), LMAN2L (16% identical).
Diseases named in the same sentence as LMAN1L in open-access papers:
LMAN1L is named in the same sentence as 6 diseases in open-access papers, as found by Europe PMC text mining. Sharing a sentence is not in itself a finding about the gene and the disease. The quoted sentences say what the papers report.
pancreatic cancer (1 paper, 2024). "High expression of LMAN1L is also associated with poor prognosis in pancreatic cancer." (PMID 39867909, 2024).
prostate carcinoma (1 paper, 2023). A carcinoma that arises from epithelial cells of the prostate gland. "Lman1l is necessary for proper excretion of the angiogenesis and tumor growth inhibitor A1AT, and loss of Lman1l has been associated with both colorectal and prostate cancers." (PMID 36765634, 2023).
tumor (2 papers, 2023 to 2024). "While there is little current research on the importance of Lman1l in BC, its high expression combined with its known molecular function may explain the lower tumor weight we observed in BSp-treated HER2/neu mice." (PMID 36765634, 2023). "We also analyzed immune cell infiltration in tumor samples from TNBC patients with different LMAN1L expression levels and found that high LMAN1L expression correlated with reduced immune cell infiltration." (PMID 39867909, 2024).
LMAN1L also shares sentences with these, for which no sentence is quoted: cancer (1 paper); leiomyoma (1); triple-negative breast carcinoma (1).